VAV1 (vav guanine nucleotide exchange factor 1)
Diseases named in the same sentence as VAV1 in open-access papers (continued):
Sharing a sentence is not in itself a finding about the gene and the disease.
breast tumors (11 papers, 2008 to 2023). "The data reported here demonstrated a peculiar role of the multidomain protein Vav1 in breast tumor cells with a triple negative phenotype, consisting in down-modulation of the oncogenic protein Akt2 through the up-modulation of the tumor suppressor miR-29b." (PMID 35743776, 2022). "In breast tumor cells, the nuclear content of Vav1 was correlated with a phenotype-specific expression of genes involved in tumor progression, including precise Akt isozymes." (PMID 35743776, 2022). "Vav1 is ectopically expressed in breast tumor cells, including TNBC derived cells, in which it promotes the down-modulation of activated Akt1, resulting in reduced tumor growth in vivo." (PMID 35743776, 2022). "We further explored the possible role of Vav1 in modulating Akt2, whose expression is phenotype‐dependent and whose role in breast tumors seems to be different from that of Akt1 and mainly associated with migration and metastasis." (PMID 29658179, 2018). "The decreased p‐Akt1 (Ser473) levels are a common effect of Vav1 upmodulation, suggesting that, in breast tumor‐derived cells and independently of their phenotype, Vav1 interferes with signaling pathways ended to specifically recruit Akt1." (PMID 29658179, 2018). "A retrospective analysis of early invasive breast tumors allowed to establish the prognostic significance of the p‐Akt/Vav1 relationship." (PMID 29658179, 2018). "Accordingly, the upmodulation of Vav1 in invasive breast tumor‐derived cells reduced their invasiveness in vitro and their metastatic efficiency in vivo." (PMID 29658179, 2018). "On the basis of our results, we can conclude that, in breast tumor‐derived cells, Vav1 is responsible of downmodulating Akt, acting at expression and/or activation levels of the different isoforms depending on tumor subtype." (PMID 29658179, 2018). "In breast tumor‐derived cell lines, divergent effects exerted by Vav1 on Rac1 activation suggest the existence of signaling pathways involving Vav1 alternative to guanosine exchange activity." (PMID 29658179, 2018). "Using in vitro and in vivo models, we demonstrated here that Vav1, ectopically expressed in invasive breast tumors derived cells, downmodulates Akt acting at expression and/or activation levels depending on tumor subtype." (PMID 29658179, 2018). "In conclusion, our findings provide new insights into the role of Vav1 in solid tumors and indicate an unprecedented function for this protein in reducing the ability of breast tumor cells to form metastasis." (PMID 24962430, 2014). "Considering the main nuclear localization of Vav1 in breast tumor cells and its correlation with their ability to give rise to distant metastasis, the possible role of Vav1 in modulating the expression of genes involved in tumor progression was investigated." (PMID 24962430, 2014). "The actual role of Vav1 in modulating invasive properties of breast tumor-derived cells was demonstrated by performing Real-time cell invasion assays with both BT-474 and MDA-MB-231 cell lines." (PMID 24962430, 2014). "In a recent study, 62% of primary breast tumors of various grades and stages were found to express Vav1 protein." (PMID 24962430, 2014). "This suggests the existence of complex mechanisms or regulation of Vav1 expression in breast tumors in vivo." (PMID 23342133, 2013). "Similar to BPGAP1, Vav1 is detected in the cytoplasm of breast tumor epithelial cells." (PMID 36598812, 2023). "Indeed, by screening the expression of Vav1 in tissue microarrays, we found a significant correlation of BPGAP1 and Vav1 expression in breast tumors." (PMID 36598812, 2023). "The evidence that none of the mice receiving cells over-expressing Vav1 developed lung aggregates of breast tumor cells suggests a protective role of the Vav1-induced miR-29b against the facilitation of extravasation of tumor cells into lung parenchyma, which was proposed to correlate with Akt2." (PMID 35743776, 2022).
breast tumors (continued). "Our further investigations have been therefore oriented to establish whether, in breast tumor as in leukemic cells, Vav1 can modulate the expression of miRNA/s, in turn responsible for targeting Akt2." (PMID 35743776, 2022). "Experiments performed with breast tumor-derived cells indicated that Vav1 negatively modulates their invasiveness in vitro and their metastatic efficiency in vivo, possibly by affecting the expression of genes involved in invasion and/or metastasis of breast tumors." (PMID 24962430, 2014). "The high levels of Vav1 we have found inside the nucleus and its accumulation in sub-nuclear structures in which it co-localizes with the speckle marker SC-35 clearly suggested a role for Vav1 in modulating nucleic acid metabolism also in breast tumor cells." (PMID 24962430, 2014). "Experiments performed with breast tumor-derived cell lines and in vivo models indicate that Vav1 may reduce the malignant potential of breast tumor cells possibly by affecting the expression of genes involved in breast tumor progression." (PMID 24962430, 2014). "The analysis of purified nuclei allowed to confirm the peculiar accumulation of Vav1 inside the nucleus of breast tumor cells, an occurrence that may justify the little amount of the protein found in total lysates from the same cell lines." (PMID 24962430, 2014). "Also unique is the role as an independent positive prognostic factor played by Vav1 in early-stage breast tumors, regardless cancer subtypes." (PMID 24962430, 2014). "Our results indicate that wild-type Vav1 is expressed in a large percentage of human breast tumors." (PMID 23342133, 2013). "As in breast tumors, Vav1 also shows a nuclear localization in PDAC, whose meaning is substantially different from that of cytoplasmic Vav1." (PMID 32993067, 2020). "In fact, as we demonstrated in breast tumors, PDAC patients with nuclear Vav1 in their primary cancer have a better prognosis than patients with only cytosolic Vav1." (PMID 32993067, 2020). "A role for Vav1 in modulating EMT has been reported in cells derived from ovarian cancer in which, at variance with breast tumor, the expression of the protein correlates with a poor prognosis of early stage patients." (PMID 24962430, 2014). "High levels of expression of all three GEFs studied Trio, Vav1 and TIAM-1 were seen in breast tumours compared with normal background breast tissue." (PMID 18925966, 2008). "High expression levels of Trio, Vav1 and TIAM-1 were seen in breast tumours, especially in those with poor prognosis." (PMID 18925966, 2008). "The study included both in vitro and in vivo models in which the effects of forcedly modulated Vav1 on the main Akt1‐related pathways were investigated primarily in breast tumor cells with a triple‐negative phenotype." (PMID 29658179, 2018). "In breast tumor-derived cells, we failed to observe any significant correlation between Vav1 and the expression levels of the epithelial marker E-cadherin as well as of the mesenchymal protein Vimentin." (PMID 24962430, 2014). "Immunohistochemical analysis with the anti-Vav1 antibody performed on TMAs revealed that almost all tumor tissues express Vav1, since the protein was absent in only 5 out of 137 examined early breast tumors." (PMID 24962430, 2014). "From the results of tissue immunohistochemistry and cell lines Western blot, higher Vav1 expression was visualized in ER positive breast tumors or cells than that in ER negative samples or cells." (PMID 24905577, 2014).
breast tumors (continued). "Here, we demonstrate that high amounts of Vav1 protein inside the nuclear compartment of cells from primary early breast tumors are positively correlated with the absence of recurrence, regardless of the histological subtypes of primary tumors." (PMID 24962430, 2014). "At variance with other solid tumors, in which the malignancy-associated role of Vav1 has been variously linked to its GEF activity, opposite effects for Vav1 on Rac1 activation were reported in AU565 and MCF7 breast tumor-derived cell lines, also in the presence of cytoskeleton changes." (PMID 24962430, 2014). "The ability of Vav1 to downmodulate p‐Akt1 is not restricted to cells with a triple‐negative phenotype, as we revealed by modulating Vav1 in cell lines representing the most frequent breast tumor subtypes." (PMID 29658179, 2018). "Overall, our data indicate that, in breast tumor‐derived cells with different phenotypes, the sole modulation of Vav1 is sufficient to affect the activation status of Akt1, involved in the insurgence and growth of breast tumors, but not of Akt2, mainly responsible of tumor metastasis." (PMID 29658179, 2018). "Despite the absence of any correlation between nuclear Vav1 and positivity/negativity to ER, we have found that the ER status of primary tumors seems to be at the basis of a close relationship of Vav1 with menopausal status of breast tumor patients." (PMID 24962430, 2014). "We also observed that at least two other Rac exchange factors, Vav1 (current study) and Dbl (not shown), are widely expressed in our panel, which suggests that total Rac activity in breast tumor cells may be determined by the cumulative activity of multiple RacGEFs." (PMID 20819206, 2010).
melanoma (11 papers, 2009 to 2025). A malignant, usually aggressive tumor composed of atypical, neoplastic melanocytes. "Furthermore, knockdown on VAV1 has been associated with a reduction in melanoma cell invasion, a key characteristic of aggressive disease." (PMID 39420530, 2025). "We confirmed a critical role for Rac1 in BRAFi resistance conferred by Vav1 and identified complex, pleiotropic mechanisms by which Rac1 and Rac1 GEFs can drive BRAFi resistance in melanoma." (PMID 41109929, 2025). "Like A375 melanoma cells expressing Vav1 or Rac1 P29S, the BRAFi-resistance phenotype of VRPP1-3 cells was blunted by the group I PAK inhibitor G-5555, confirming that group I PAKs can also contribute to spontaneous Rac1-driven BRAFi resistance." (PMID 41109929, 2025). "Several melanoma cell lines also express wild-type Vav1, including the highly metastatic BLM cells, although the level of protein expression was low and it was localized in the cell periphery near the plasma membrane." (PMID 26353933, 2015). "Vav1 was found to be expressed in the majority of human neuroblastomas and pancreatic ductal adenocarcinomas, in over 40% of human primary lung cancers and melanomas and in greater than 50% of ovarian cancers." (PMID 24962430, 2014). "As a GDP/GTP exchange factor, Vav1 is also involved in CXCL12-promoted invasion of melanoma cells." (PMID 24905577, 2014). "We recently found that upregulation of DBL family guanine exchange factors (GEFs), such as Vav1, can promote BRAFi/MEKi resistance in BRAF V600-mutant melanoma cells." (PMID 41109929, 2025). "Knockdown of Vav1 by RNAi in melanoma cells led to impaired activation of the Jak/Vav1/RhoGTPases (Rac1 and RhoA) pathway, blocking up-regulation of MT1-MMP by CXCL12, a mechanism that contributes to melanoma cell invasion." (PMID 25313137, 2014). "Monomeric GTPases such as Rac1 are activated by guanine exchange factors (GEFs), and we previously identified upregulated DBL family member GEFs, including Vav1, as drivers of resistance to BRAF inhibitors (BRAFi) in a forward genetic screen using BRAF-mutant melanoma cells." (PMID 41109929, 2025). "Importantly, we have recently described experiments that functionally validated the role of four of these candidates (VAV1, MCF2, BRAF, RAF1) in driving vemurafenib resistance in human melanoma cell lines." (PMID 31208320, 2019). "In addition, Vav1 is a potent regulator of transendothelial migration of leukocytes, and also contributes to CXCL12-induced MT1-MMP expression and invasion by melanoma cells." (PMID 26353933, 2015).
multiple sclerosis (8 papers, 2016 to 2024). A progressive autoimmune disorder affecting the central nervous system resulting in demyelination. "For example, recent studies have linked VAV1 single nucleotide polymorphisms (SNP) with the degree of severity of rheumatoid arthritis, multiple sclerosis and other autoimmune diseases." (PMID 34205377, 2021). "SNPs found in the rat Vav1 locus have also been associated with the severity of autoimmune encephalomyelitis (the rat model for multiple sclerosis) and pristane-induced autoimmune arthritis." (PMID 34205377, 2021). "Genetic association studies revealed the implication VAV1 as a risk factor for several immune-mediated diseases, such as multiple sclerosis, rheumatoid arthritis and MG." (PMID 30410484, 2018). "We believe that this might be physiologically relevant, since our previous study showed that the Vav1 risk allele is associated with increased mRNA expression levels in PBMCs from healthy donors and multiple sclerosis patients, which is positively correlated to IFN-γ and TNF expression." (PMID 38565808, 2024). "In addition, our findings are fully in line with our previous study using cohorts of patients with multiple sclerosis, in which we demonstrated a strong association between Vav1 expression, susceptibility to multiple sclerosis and production of inflammatory cytokines by CD4 T cells." (PMID 27438086, 2016). "Disrupting the interactions between EZH2 and Vav1 formed frequent, enlarged focal adhesions that were connected to stress fibers in DCs, impairing the transendothelial migration and restricting multiple sclerosis progression." (PMID 35281921, 2022). "Expression levels for EZH2, TLN1, and VAV1 were significantly decreased in PBMC from the whole multiple sclerosis group compared to controls." (PMID 30367633, 2018). "The majority of reported nominally significant associations overlap with previously reported susceptibility loci for RA; overlaps with other autoimmune diseases were observed for UBE2D1 associated with Crohn’s disease, PRDM1 with systemic sclerosis, and VAV1 with multiple sclerosis." (PMID 34101054, 2021). "VAV1 proteins are involved in osteogenesis, lymphopoiesis, cardiovascular homeostasis and the function of the neuronal system, and they play an important role in the pathogenesis of some diseases such as cancers, autoimmune diseases and multiple sclerosis." (PMID 32380774, 2020). "Further stratification of the multiple sclerosis group into the different clinical forms revealed significantly decreased gene expression levels of EZH2, TLN1, and VAV1 in PBMC from RRMS, SPMS, and PPMS patients compared to HC." (PMID 30367633, 2018).
neuroblastoma (8 papers, 2012 to 2023). Neuroblastoma (NB) is the most common solid, extracranial childhood tumor. "Vav1 was recently implicated in several human cancers, including neuroblastoma, lung, and pancreatic." (PMID 30380781, 2018). "For example, VAV1 protein from SK-N-MC neuroblastoma cells was similar to wild-type VAV1 in terms of molecular size, phosphorylation state, and ability to associate with tyrosine-phosphorylated EGFR through its SH2 domain." (PMID 37174676, 2023). "Others and we detected ectopic expression of Vav1 in neuroblastoma, pancreatic, lung and breast cancers." (PMID 25313137, 2014). "The involvement of wild type Vav1 in human tumors was first demonstrated in the neuroblastoma SK-N-MC cell line." (PMID 23342133, 2013). "Katzav’s laboratory was the first to report VAV1 overexpression in human neuroblastoma specimens, suggesting that when VAV1 is expressed in tissues other than hematopoietic tissues, it may be involved in cancer." (PMID 37174676, 2023). "Ectopic Vav1 expression was first noted in the neuroblastoma SK-N-MC cell line." (PMID 26353933, 2015). "A subsequent screen of 42 primary human neuroblastoma tumors revealed that the majority (76%) expressed Vav1, suggesting for the first time that ectopic expression of wild type Vav1 might contribute to human cancer." (PMID 26353933, 2015). "A subsequent screen of 42 primary human neuroblastomas revealed that the majority expressed Vav1." (PMID 23342133, 2013).
pancreatic ductal adenocarcinoma (8 papers, 2012 to 2025). An infiltrating adenocarcinoma that arises from the epithelial cells of the pancreas. "The Vav family exemplifies this complexity, where aberrant Vav1 expression in pancreatic ductal adenocarcinoma (PDAC) synergizes with KRAS mutations to drive malignant transformation." (PMID 41020039, 2025). "Ectopic expression of VAV1 occurs in a variety of cancer types, including pancreatic ductal adenocarcinoma (PDAC), breast cancer, gastric cancer, esophageal squamous cell carcinoma, and others, and is often associated with poorer survival rates." (PMID 41314543, 2025). "Using pancreatic ductal adenocarcinoma (PDAC)-derived cells, we also revealed that the ATRA induced up-modulation of Vav1 is essential for the retinoid-induced trans-differentiation of neoplastic cells into insulin producing cells." (PMID 33165749, 2021). "Wild-type Vav1 and mutant K-Ras synergistically accelerate pancreatic acinar-to-ductal metaplasia (ADM), thus leading to pancreatic ductal adenocarcinoma (PDAC), depending on Vav1’s activity as a GEF for Rac1." (PMID 32277014, 2020). "To explore the contribution of Vav1, a hematopoietic signal transducer, to pancreatic ductal adenocarcinoma (PDAC) development, we generated transgenic mouse lines expressing, Vav1, K-RasG12D, or both K-RasG12D and Vav1 in pancreatic acinar cells." (PMID 32277014, 2020).
acute myeloid leukemia (6 papers, 2009 to 2023). Acute myeloid leukemia (AML) is a group of neoplasms arising from precursor cells committed to the myeloid cell-line differentiation. "Vav1 was shown to be required ATRA-induced differentiation in acute myeloid leukemia (AML) cell lines to neutrophils and to maturation of these same cell lines to monocytes/macrophages following PMA treatment." (PMID 35326399, 2022). "To explore the involvement of other miRNA/s with a known role in targeting Akt2, we focused on miR-29b, whose gene transcription is positively regulated by Vav1 in acute myeloid leukemia and in MDA-MB-231 cells and that is known to target Akt2 in glioblastoma, gastric and ovarian cancers." (PMID 35743776, 2022). "In the case of the VAV1 mRNA, we found a significant downmodulation in a small subgroup of samples derived from patients affected by diffuse large B–cell lymphoma, chronic lymphocytic leukemia, and acute myeloid leukemia." (PMID 20011522, 2009). "VAV1 expression was also significantly higher in acute myeloid leukemia (AML) patients than in control tissues." (PMID 37174676, 2023).